LOXL2 (lysyl oxidase like 2)
Diseases named in the same sentence as LOXL2 in open-access papers (continued):
Sharing a sentence is not in itself a finding about the gene and the disease.
tumor (continued). "Among collagen cross-linking enzymes, Lysyl oxidase-like 2 (Loxl2) mRNA was significantly and specifically decreased in WlsΔOB-OS tumor-bearing bones and primary OS cells." (PMID 32686768, 2020). "The application of a novel and highly selective small molecule inhibitor of LOXL2-attenuated tumor growth and metastatic spread to a significant degree in both mouse models." (PMID 31086173, 2019). "Although the growth conditions were different for the HepG2 and Bel7402 groups, LOXL2 promoted tumour growth in both the HepG2‐LOXL2 cell‐engrafted tumours and Bel7402‐control cell‐engrafted tumours." (PMID 30506621, 2019). "Inhibition of LOXL2 activity by administration of PXS-S1C to mice reduced tumor cell proliferation, accompanied by changes in morphology and in the expression of epithelial to mesenchymal transition markers." (PMID 31086173, 2019). "Accordingly, inhibition of LOX and of LOXL2 significantly reduces tumor growth and metastasis in various cancer models." (PMID 31130685, 2019). "Expression levels of LOXL2 were markedly increased in matched adjacent non-tumor tissue compared with levels in tumor tissue samples, and this difference gradually increased with higher histological grade and more advanced hepatocellular tumors." (PMID 30986934, 2019). "This study identified the first molecular mechanism for LOXL2 in the promotion of cancer via its enzymatic modification of a non-collagenous substrate in the context of paracrine signaling between tumor cells and resident fibroblasts." (PMID 31086173, 2019). "We further investigated the effects of LOXL2 effects on tumourigenic potential, growth, migration and progression in vivo using a subcutaneous xenograft tumour model." (PMID 30506621, 2019). "LOXL2 inhibition was found to attenuate tumor growth in tongues as determined by caliper measurements." (PMID 31086173, 2019). "We investigated mechanisms by which tumor cell secreted LOXL2 targets proximal mesenchymal cells to enhance tumor growth and metastasis." (PMID 31086173, 2019). "Both LOX and LOXL2 have been positively involved in neovascularization, although most of the approaches were focused on tumor angiogenesis." (PMID 31615160, 2019). "By contrast, LOXL2 staining occurred throughout the specimen in both tumor cells and in surrounding stroma." (PMID 31086173, 2019). "The expression of LOXL2 was also specifically induced in tumor endothelial cells which LOXL2 blockade with AB0023 limited tumor vascularization." (PMID 31615160, 2019). "Further, overexpression of both LOX and LOXL2 increased tumor perfused vessel density in different syngeneic models." (PMID 31615160, 2019). "Tumor suppressive microRNA-26a/b and microRNA-29s directly inhibited LOXL2 to reduce RCC cell migration and invasion." (PMID 29732010, 2018). "LOXL2 remodels the tumor microenviroment, regulates cell adhesion, invasion, and motility, and improves tumor cell survival and chemoresistance." (PMID 29732010, 2018). "These tumor permeation studies demonstrated that in the LOX/LOXL2 OE tumors only few cell layers surrounding the blood vessels are well supplied with H33342 and that small molecules barely permeate into the dense surrounding tissue." (PMID 29780168, 2018). "Conversely, TGF-β abrogated tumor cell-co-culture-dependent augmentation of LOXL2 and ADAMTS12 expression in patient 21 N-MSCs (right column)." (PMID 29503225, 2018). "Multicellular tumor spheroids (MCTS) generated from LOX or LOXL2 overexpressing 4T1 cells were reduced in size." (PMID 29780168, 2018). "LOX/LOXL2 overexpression in human clear cell renal cell carcinoma (ccRCC) promoted tumor cell migration and adhesion, as well as matrix stiffness to enhance tumor progression and metastasis." (PMID 29732010, 2018). "LOX and LOXL2 as primary tumor-derived soluble factors contribute to formation of pre-metastatic niches in distant target organs." (PMID 29728125, 2018).
tumor (continued). "And how cancer cell-derived LOXL2 can regulate HCC progression in hypoxic tumor microenvironment gained better understand." (PMID 28449718, 2017). "For the first time, our data reveal that the tumor‐promoting role of LOXL2 in ESCC probably perturbs the architecture of the actin cytoskeleton through its PPIs and induces additional oncogenic effects by hyperactivation or loss‐of‐function of key proteins." (PMID 28556501, 2017). "In conclusion, our data reveal that the tumor‐promoting role of LOXL2 in ESCC is mediated by perturbing the architecture of actin cytoskeleton through its PPIs." (PMID 28556501, 2017). "Our data indicate that the specific inhibition of LOXL2 alone will delay primary tumor growth, suggesting a LOXL2 specific role in primary tumor growth." (PMID 28199967, 2017). "Here we see a more significant effect whereby genetic silencing of LOXL2 in primary tumor cells leads to both a significant decrease in Ki67 expression and an increase in cleaved caspase-3." (PMID 28199967, 2017). "Secretion of LOXL2 by both stromal and tumor cells, for instance, is involved in fibroblast activation within the TME." (PMID 28553358, 2017). "Inhibition of LOXL2 activity inhibited the growth of primary tumors and reduced primary tumor angiogenesis." (PMID 28199967, 2017). "Recently, a LOXL2‐specific monoclonal antibody (AB0023/4) was shown to be effective against primary tumor growth and reduce metastatic burden in mouse models." (PMID 28556501, 2017). "Nonetheless, the LOX/LOXL expression profile detected in normal and tumor-associated pericytes differed from the one exhibited by endothelial cells, in which LOX and LOXL2 are the predominantly expressed family members." (PMID 28553358, 2017). "Recent work has demonstrated that HIF-1α promotes the expression of LOXL2, which is believed to amplify tumor aggressiveness." (PMID 28449718, 2017). "All together our results demonstrate that dormant MCF-7 cells will escape tumor dormancy upon LOXL2 expression." (PMID 27655685, 2016). "All together, our results demonstrate that EMT induced by LOXL2 expression in dormant MCF-7 cells promoted their emergence from tumor dormancy to proliferative growth and the CSC-like population mediated this transition." (PMID 27655685, 2016). "On univariate and multivariate analyses, tumor stage and LOXL2-positive status were identified as independent prognostic factors for DFS." (PMID 27285767, 2016). "Here we show that EMT induced by LOXL2 expression in DTC promoted their transition from tumor dormancy to proliferative growth in the 3D BME system, whereas cells that retained their epithelial phenotype remained dormant." (PMID 27655685, 2016). "In keeping with our results obtained with subcutaneous xenografts, LOXL2 injection prevented the tumor growth slowdown induced by gemcitabine, and LOXi countered this LOXL2-induced resistance to gemcitabine." (PMID 27050073, 2016). "On univariate analysis, combined resection of major vessels, depth of invasion, tumor stage, and LOXL2- positive status were significant factors for poor prognosis." (PMID 27285767, 2016). "Specific upregulation of the LOXL2 protein is found in EOC endothelial cells, where inhibition of LOXL2 reduced endothelial cell concentration within the tumor." (PMID 26579497, 2015). "Tumor-derived lysyl oxidase-like 2 (LOXL2) promotes the expression of α-smooth muscle actin (α-SMA) and activates fibroblasts through integrin-mediated FAK activation and AKT signaling." (PMID 25918719, 2015). "Aberrant LOX, LOXL2, and LOXL4 expression are implicated in dysregulating the ECM and inducing a malignant phenotype and promoting tumor progression in EOC." (PMID 26579497, 2015). "Upregulation of LOXL2 has been detected in many tumor cell lines or clinical samples and also closely correlates with tumor invasion and metastasis." (PMID 25254241, 2014).
tumor (continued). "One of the upregulated proteins, lysyl oxidase like 2 (LOXL2), was of specific interest given its role in extracellular matrix (ECM) remodeling and its association with the formation of tumor metastases." (PMID 26082068, 2012). "An experimental study recently investigated the effects of a LOXL2-specific monoclonal antibody on tumor characteristics." (PMID 22509805, 2012). "Over-expression of both HIF1A and LOXL2 was observed only in the surgically resected tumor tissues obtained from different cases." (PMID 21533028, 2011). "LOXL2 has previously been reported to be involved in an invasiveness process and specifically expressed by fibroblasts in tumour tissue." (PMID 20051100, 2010). "Using our assay we show for the first time that inhibition of endogenous Loxl2 expression in several types of tumor cells strongly inhibits their invasiveness." (PMID 19948022, 2009). "The increased invasiveness was subsequently attributed to Loxl2 induced inhibition of E-cadherin expression in tumor cells." (PMID 19948022, 2009). "We observed increased mRNA expression for STC1 and LOXL2 in tumour tissue, consistent with previous reports." (PMID 18590575, 2008). "Importantly, we provide the first evidence that this axis regulates LOXL2, a key enzyme in extracellular matrix crosslinking, thereby promoting tumor cell migration and potentially contributing to metastatic niche formation." (PMID 41399365, 2026). "Additionally, novel oral aminomethy-lthiophene-based compounds, acting as dual LOX/LOXL2 inhibitors, have emerged as promising candidates due to their excellent bioavailability and anti-tumor activity." (PMID 41362727, 2026). "Notably, elevated LOXL2 expression consistently correlated significantly with poor prognosis across all tumour types." (PMID 40179101, 2025). "However, knock-down of LOXL2 in MDA-MB-231 cells led to a reduced proliferation of tumor cells and an increase in the percentage of p27-positive MDA-MB-231 cells." (PMID 41185039, 2025). "Furthermore, heightened matrix stiffness stimulates the expression of LOXL2 in tumor cells via integrin β1/α5/JNK/c-JUN signaling pathways, promoting the production of FN and MMP9." (PMID 40211368, 2025). "LOXL2 may affect the dynamic balance of the tumor microenvironment by regulating the immune function of macrophages and neutrophils in the extracellular matrix (ECM)." (PMID 40756111, 2025). "This discovery not only deepens our understanding of how age-related changes in the ECM influence tumor progression but also suggests that LOXL2+ PSCs could serve as a potential therapeutic target in PDAC." (PMID 40425551, 2025). "scRNA-seq localized LOXL2 in tumor cells, stroma, and macrophages." (PMID 40756111, 2025). "Subcutaneous coimplantation experiments further confirmed that, compared with the control group (Vector-LOXL2.HPSCs+MIA PaCa-2 group), the LOXL2-OE group (OE-LOXL2.HPSCs+MIA PaCa-2 group) exhibited significant tumor-promoting effects, with tumors displaying greater linear ECM alignment." (PMID 40425551, 2025). "LOXL2 was specifically highly expressed in cluster 7, which was located in the Tumor Cell Area defined by us and may be a key marker, suggesting that LOXL2 is closely related to tumors." (PMID 40756111, 2025). "Moreover, the HIF-1α/LOXL2 axis further promotes tumor progression and metastasis by regulating oncogenes such as CENPF and ATAD2, activating mitotic and cell growth pathways, thereby synergistically amplifying the pro-VM effect of HIF-1α." (PMID 41019994, 2025). "Moreover, other studies have shown that stromal depletion—through Hedgehog inhibition, epithelial Sonic hedgehog deletion, fibroblast ablation, or lysyl oxidase-like 2 inhibition—can increase tumor vascularity, accelerate metastasis, and shorten survival." (PMID 41049608, 2025). "Importantly, through integrative machine learning approaches, we identified four hub genes (MGP, LOXL2, FSTL3, and PFN2) that are closely associated with tumor development and progression." (PMID 41395115, 2025).
tumor (continued). "The findings indicated a reduction in the fluorescence area fraction and mean fluorescence intensity of LOX and LOXL2 in the tumour region of individuals showing sensitivity to neoadjuvant chemotherapy compared to those exhibiting resistance, although statistical significance was not achieved." (PMID 40179101, 2025). "Preclinical studies suggest that LOXL2 inhibition may soften the fibrotic scaffold by reducing matrix density and facilitating immune cell infiltration into tumor nests, although clinical translation remains in its early stages." (PMID 41013723, 2025). "When compared to the effect of recombinant PEAR1 on tumor cell growth and expression of p27, the effect of a suppression of LOXL2 in tumor cells was much smaller, indicating that binding and sequestration of LOXL2 by PEAR1 can only partially explain the dormancy-inducing activity of PEAR1." (PMID 41185039, 2025). "LOX and LOXL2 are genes upregulated by hypoxia, promoting tumour cell invasion and metastasis." (PMID 40179101, 2025). "Prior research demonstrated that LOXL2 released by tumours induced ECM remodelling, leading to heightened stromal stiffness, and stimulated surrounding CAFs via integrin‐mediated focal adhesion kinase (FAK) activation or extracellular signal‐regulated kinase (ERK) activation." (PMID 40179101, 2025). "Additionally, the capacity of tumor cells to undergo apoptosis was enhanced considerably by the silencing of LOXL2." (PMID 39877633, 2025). "High expression of LOXL2 is related to tumor cell proliferation, invasion, and metastasis." (PMID 38810697, 2024). "Furthermore, the roles of LOXL2 in tumor progression and cellular senescence were partly verified in vitro." (PMID 38922489, 2024). "Overall, a higher level of LOXL2 expression has been detected in tumor tissues, compared to normal tissues, indicating that LOXL2 may contribute to tumor pathogenesis through multiple potential mechanisms." (PMID 38922489, 2024). "Furthermore, proteomic profiling of primary prostate tissue cornered Lysyl Oxidase Like 2 (LOXL2) protein as a tumor microenvironment regulator involved in migration and extracellular matrix remodeling." (PMID 39452071, 2024). "Different single tumor studies showed disparate effects of LOXL2 on immune cell infiltration." (PMID 38922489, 2024). "In addition, AB0023, a neutralizing antibody against LOXL2, can inhibit the activity of LOXL2, reduce activated fibroblasts, and inhibit tumor progression." (PMID 38246995, 2024). "Additionally, we validated the impacts of LOXL2 on tumor proliferation, migration, and cellular senescence in vitro." (PMID 38922489, 2024). "By suppressing LOXL2-directed early angiogenesis, the growth of the primary tumor was inhibited." (PMID 38672570, 2024). "LOXL2 showed significant correlation with tumor invasion and progression, and its overexpression may negatively impact the prognosis of HNSC patients." (PMID 39012409, 2024). "Notably, AOC3, F8, and IL1A were found to be highly expressed in the normal group, while COA6, FKBP4, and LOXL2 were highly expressed in the tumours." (PMID 38577594, 2024). "Macrophages both express their own LOXL2 and promote its expression in tumor cells." (PMID 39555068, 2024). "LOXL2 can reduce the drug concentration in the tumor during chemotherapy." (PMID 38725864, 2024). "Based on the inverse correlation found between elevated LOXL2 expression levels and overall survival, disease-free survival, and clinicopathological parameters in patients with different tumour types, numerous studies have focused on the regulation of LOXL2 expression in the last two decades." (PMID 37762708, 2023). "Additionally, LOXL2 can promote tumour metastasis by regulating the levels of phosphorylated AKT through mechanisms that are not yet fully understood and by stabilising integrin subunits α5 (ITGA5) and β1 (ITGB1)." (PMID 37762708, 2023).
tumor (continued). "However, anti-Loxl2 mAb treatment in a PDAC transplantation mouse model has caused a significant reduction in matrix content and accelerated tumor growth." (PMID 37156840, 2023). "In oral tumour cells, secreted LOXL2 oxidises lysine residues in platelet-derived growth factor receptor beta (PDGFRβ) on stromal fibroblasts, enhancing platelet-derived growth factor (PDGF-AB) signalling and promoting stromal fibroblast proliferation via ERK activation." (PMID 37762708, 2023). "LOXL2 participates in the repression of E-cadherin CDH1, a hallmark of the epithelial to mesenchymal transition (EMT) that is believed to amplify tumor aggressiveness, suggesting that it may play a role in tumor progression." (PMID 37056396, 2023). "The function of EPHA2, LAMC2 and LOXL2 in tumor cells may explain the correlation between the VM score and poor prognosis of LUAD patients." (PMID 37351348, 2023). "The miR-RNA-29 family members (miR-29a/b/c) also downregulate LOXL2 mRNA in other tumour contexts." (PMID 37762708, 2023). "Tumor growth was slow in mice administered with Mia GR, in which LOXL2 was knocked down." (PMID 37737908, 2023). "Although this finding requires further study, it may lead to the expansion of the pathways that LOXL2 uses to modulate tumour progression." (PMID 37762708, 2023). "LOXL2 was associated with tumour suppression, cell adhesion and ageing but not with ID or neurodevelopmental abnormalities." (PMID 37550884, 2023). "The expression of the lysyl oxidase isoforms LOX and LOXL2 in human A375 melanoma cells were confirmed both at the level of the isolated cells and in the tumour tissue by Western blot analysis, demonstrating the suitability of the corresponding xenograft model." (PMID 37565736, 2023). "LOXL2 is a member of the amine oxidase family, which plays a role in the formation of crosslinks in stromal collagens and elastin, as well as cell motility, tumor development, and progression." (PMID 37886979, 2023). "In this review, we highlight the significant progress made in the last two decades regarding LOXL2 expression patterns in tumour samples, the mechanisms regulating its expression levels, targets influencing tumour progression, and the valuable insights gained from genetically modified mouse models." (PMID 37762708, 2023). "The finding of these RBPs as potential partners for LOXL2 allows us to hypothesize the modulation of RBPs’ function as a new molecular mechanism of LOXL2’s action in tumor progression." (PMID 37298909, 2023). "Given the fact that it has been associated with cancer progression and invasiveness, we wondered whether the expression of LOXL2 could be used to predict tumor response to standard chemotherapeutic drugs." (PMID 37937685, 2023). "In addition, miR-26a was reported to have tumor-suppressive functions, affecting tumor cell migration by regulating lysyl oxidase like 2 (LOXL2)." (PMID 37444397, 2023). "Because these functions are most likely catalytic independent, it may suggest that Loxl2 plays a more diverse role in tumor biology than Loxl3." (PMID 35292774, 2022). "Studies demonstrated that elevated levels of LOXL2 might contribute to tumor progression and metastasis by promoting tumor cell invasion and remodeling of the tumor microenvironment." (PMID 36254230, 2022). "This LOXL2/L2Δ13-induced reorganization may also trigger aldolase release into the cytoplasm to further enhance tumor progression." (PMID 36209516, 2022). "Circulating and dissociated tumor cells isolated from KPC GEMM mice that were grown subcutaneously were strongly positive for Loxl2 indicating that the cancer cells in circulation also have high expression of Loxl2 protein." (PMID 36002889, 2022). "The aberrant expression of lysyl oxidase–like 2 (LOXL2) is associated with fibrotic disorders and metastatic/invasive tumors, and LOXL2 has shown to promote activation of fibroblasts, proliferation and metastasis/invasion of tumor cells, and tumor angiogenesis." (PMID 36362176, 2022).